IL4 (interleukin 4)
Diseases named in the same sentence as IL4 in open-access papers (continued):
Sharing a sentence is not in itself a finding about the gene and the disease.
colon carcinoma (continued). "After the administration of a neutralizing antibody against IL-4 in a murine model of breast and colon cancer, increased antitumor immunity and delayed tumor progression were reported." (PMID 33255425, 2020). "Treatment with an IL-4Rα antagonist or anti-IL-4 neutralizing antibody enhanced the antitumor efficacy of standard drugs and confirmed the autocrine mechanism of IL-4 in CSCs in colon cancer." (PMID 30841635, 2019). "Similar experiments utilizing IL-4-treated DLD-1 colon cancer cells confirmed the plasma membrane location of the NOX1 that had been produced." (PMID 28498822, 2017). "In prostate cancer, blocking of IL-4-pathway reduced Ki67 expression, and in colon cancer IL-4-withdrawal strongly increased chemotherapy-induced apoptosis." (PMID 28350325, 2017). "The same authors then demonstrated that consecutive exposure to low doses of SKA IL-4 and IL-12 enhances the immunostimulatory functions of dendritic cells from early-stage colon cancer patients." (PMID 29244717, 2017). "In line with delayed clearance, H. polygyrus infected mice suffering from colon cancer produced significantly less IL-4 in response to the parasites." (PMID 28938014, 2017). "IL-4 dependent resistance of colon cancer cells is likely a tumor autocrine process that establishes an anti-apoptotic program in cancer stem-like cells, and protects them from chemotherapy." (PMID 28927416, 2017). "The relationship between IL-4Rα and NOX1 in these tumors and adjacent normal tissues suggests that the conditions exist in the clinic to support a mechanistic relationship between IL-4 and colon cancer proliferation." (PMID 28498822, 2017). "In concert with these results, we found that IL-4 increased NOX1 expression in other colon cancer lines, including DLD-1, WiDr, NCI-H508, and SW403 cells." (PMID 28498822, 2017). "Treatment of colon carcinoma HT-29 cells with IL-4 and TNFα led to an increase in fibronectin adhesion in vitro with a corresponding decrease in lung colonizing potential in vivo." (PMID 27556857, 2016). "The effects of IL-4 signaling have been studied extensively in the development of colon cancer: one study found pro-proliferative effects of IL-4Rα signaling in mouse colon tumors, as well as human and mouse colon adenocarcinoma cell lines examined in vitro." (PMID 24672527, 2014). "Blockage of IL-4 resulted in downregulation of anti-apoptotic proteins, such as Bcl-xL, suggesting that IL-4 protects colon cancer cells from cytotoxic drugs by inhibiting apoptosis." (PMID 24728412, 2014). "It supports the cellular proliferation in human colon cancer cell lines in a concentration-dependent manner, whereas in pancreatic cancer IL-4 is an autocrine growth factor." (PMID 25208941, 2014). "To investigate the specific inhibition of GO-Y030, we detected the phosphorylation of STAT3, STAT1, or STAT6 induced by IL-6, IFN-γ, or IL-4 in HT29 colon cancer cell lines." (PMID 21694723, 2011). "On the other hand, our results contradict reports where IL-4 treatment has been shown to elevate MUC2 levels by a MAPK pathway in human colon cancer cells." (PMID 16551361, 2006). "Furthermore, stimulation of the human colon cancer cell line LS174T with IL-4 alone increased MUC2 mRNA expression by approximately twofold, suggesting that cytokines can influence mucin production." (PMID 40944230, 2025). "In addition, we observed a reduction in IL‐17A and IL‐4 levels but increased IFN‐γ RNAm levels in the colonic tumors of the Mgl1−/− mice; IL‐17A and IL‐4 are cytokines supporting colon tumor growth, whereas IFN‐γ has antitumorigenic functions." (PMID 40033767, 2025). "investigating the binding characteristics of IL-4 in human colon carcinoma cell lines." (PMID 39502691, 2024).
colon carcinoma (continued). "The identification of drug-resistant cancer stem cells (cr-CSCs) originated from research on colon cancer cells resistant to chemotherapy, which maintain their resistance through autocrine interleukin-4 (IL-4) signaling to increase anti-apoptotic protein expression." (PMID 39184916, 2024). "in 2007, this study used colon cancer stem cells to demonstrate that CD133+-expressing colon cancer stem cells could produce and utilize IL-4 to protect themselves from apoptosis, thereby resisting chemotherapy." (PMID 36110958, 2022). "As HSD3B1 is essential for steroid hormone biosynthesis, our results suggest that IL4 may play a crucial role in the regulation of active steroid synthesis in colon cancer cells." (PMID 36362361, 2022). "Conversely, our results suggest that GSK3 is a novel positive regulator of IL4-induced steroidogenesis and may contribute to steroid production in colon cancer cells." (PMID 36362361, 2022). "The significant increase in the level of interleukin such as IL-1, IL-4, IL-6 was recorded in colon cancer patients (17.26 ± 2.49 pg/ml, 32.18 ± 1.45 pg/ml, 28.26 ± 1.88 pg/ml) as compared to controls (6.35 ± 1.07 pg/ml, 21.25 ± 2.18 pg/ml, 9.58 ± 3.33 pg/ml), respectively." (PMID 34096454, 2021). "IL-4, which is abundant in the tumor microenvironment, increases survivin protein expression in human macrophages, which is in agreement with a recent report describing that survivin expression and location are regulated by IL-4 in colon cancer stem cells through a STAT6-dependent pathway." (PMID 33710603, 2021). "In addition, it has been found in colon cancer that the Notch signaling pathway in colon cancer cells can affect the polarization and recruitment of TAMs by secreting IL-4." (PMID 32943090, 2020). "Therefore, we believe SPHK1, TREG, CASP9 and IL4 can be regarded as potential drug targets that are critical for the treatment of colon cancer." (PMID 31138124, 2019). "CD133+ CSCs in colon cancer are resistant to apoptosis due to production of IL-4." (PMID 30841635, 2019). "These experiments suggested that ROS generated by NOX1 might affect IL-4/IL-13-dependent signal transduction events in colon cancer." (PMID 28498822, 2017). "Furthermore, IL-4 contributes in MUC2 regulation in colon cancer and its addition to cancer cells increases MUC2 secretion through a MAP kinase pathway, leading to the so-called mucinous carcinomas." (PMID 28927416, 2017). "In addition, IL-4 protects the tumorigenic CD133+ CSCs in human colon carcinoma from apoptosis, and the anti-IL-4 antibody or IL-4R alpha antagonists induces apoptosis of CSCs and markedly sensitizes them to chemotherapeutic drugs." (PMID 24823879, 2014). "CD133-expressing colon cancer cells produce interleukin 4 (IL-4) as an autocrine growth factor." (PMID 22433494, 2012). "Increased MUC2 mRNA was noted by quantitative RT-PCR analysis in human colon cancer cell lines in response to a single stimulation with IL-4 (approximate two-fold increase in comparison to baseline), IL-13, and TNF-α (c.2.5-fold increase in MUC2 mRNA) via MAP kinase pathways." (PMID 21152122, 2010). "The expression of mRNA of 3 out of 8 tested isoenzymes governing O-glycosylation of mucins (polypeptide N-acetylgalactosaminyltransferases) in a colon cancer cell line, was also noted to be upregulated by the Th2 cytokine IL-4, resulting in increased incorporation of GalNAc into mucin o-glycans." (PMID 21152122, 2010). "MSCs can prevent the progression of colon cancer by inducing Treg accumulation via TGF-β at the early stage of inflammatory transformation but promote the progression of colon cancer by inducing a shift in Th1/Th2 immune balance to Th2 through IL-4 secretion at the late stage." (PMID 36978120, 2023).
colon carcinoma (continued). "MSCs can curb the progression of colon cancer by inducing Treg accumulation via TGF-β at the early stage of inflammatory transformation but promote the progression of colon cancer by inducing a shift in Th1/Th2 immune balance to Th2 through IL-4 secretion at the late stage." (PMID 36978120, 2023). "Hence, CSC-derived IL-4 acted as both a paracine and autocrine survival factor in colon cancer." (PMID 24728412, 2014). "These macrophages show high STAT6‐related gene expression, induced by IL4 and IL13 exposure, which is a central mechanism in colon cancer development and progression." (PMID 38037545, 2023). "A downregulation of miR-195-5p has been previously reported in colon cancer tissue as a regulator of the EMT and M2-like TAM polarization through the NOTCH2-GATA3/IL-4 axis." (PMID 35453669, 2022). "IL4 stimulates 3β-HSD activity in various cancer cells, including breast, cervical, and colon cancer cells." (PMID 36362361, 2022). "In this study, we demonstrated that IL4 greatly increased the HSD3B1 expression at both the mRNA and protein levels in the HT-29 colon cancer cells." (PMID 36362361, 2022). "In colon cancer, the autocrine expression of CSC-secreted IL-4 promotes apoptosis evasion mechanisms, and treatment with IL-4 antibody especially sensitizes this subpopulation, promoting the efficacy of standard chemotherapeutic drugs." (PMID 33059744, 2020). "Mechanistically, PKN2 suppresses the expression of IL4 and IL10 from colon cancer cells by inhibiting Erk1/2 phosphorylation, which is required for phosphorylation and binding of CREB and Elk-1 to the promoters of IL4 and IL10." (PMID 29368606, 2018). "Furthermore, both IL-4 and IL-13 may contribute to colon cancer progression." (PMID 29922293, 2018). "Significantly decreased IL4 and IL10 levels were found in PKN2 overexpression colon cancer cells, while profoundly increased IL4 and IL10 expression was detected in PKN2-depleted cells." (PMID 29368606, 2018). "IL-4 and IL-13 increased the expression of NADPH oxidase 1 in human colon cancer cell lines, which led to the production of reactive oxygen species and cellular proliferation." (PMID 29922293, 2018). "To evaluate the generality of these observations, we also examined the effect of IL-4 exposure on ROS production and tumor cell proliferation in DLD-1 human colon cancer cells." (PMID 28498822, 2017). "Taken together, these data provide evidence demonstrating that IL-4 and IL-13 upregulate NOX1 in colon cancer cells though the IL-4R/STAT6 pathway, and that GATA3 plays an important role in the transcriptional regulation of NOX1." (PMID 28498822, 2017). "Treatment with conditioned medium of colon cancer cells increased macrophage expression of the M2-related markers arginase-1 (Arg1), CCL17, CCL22, IL-10 and IL-4." (PMID 27683110, 2016). "One potential candidate in this respect is the cytokine interleukin-4 (IL-4), given that it can increase CB1 receptor expression, and that both IL-4 and IL-4 receptors are found in colon tumours." (PMID 21901119, 2011). "It is reported that both IL4 and IL13 share signalling events in human colon carcinoma cell lines (HT29 and WiDr), and that both IL13 and IL4 induce phosphorylation of IL4 STAT (STAT6)." (PMID 12402156, 2002). "Furthermore, combining Fc–IL‐4 and ICB resulted in a complete tumour clearance (100%) in the MC38 colon cancer model." (PMID 39739593, 2025). "In line with the previous research of our research group, colon cancer CT26.WT was selected for the transwell assay, and the transwell assay results showed that treatment with IL-4-conditioned medium (CM) obviously enhanced the migratory ability of the cells when compared with the control group." (PMID 35889289, 2022). "In colon cancer, CSC-secreted IL-4 promotes their maintenance and inhibits apoptosis." (PMID 33059744, 2020).
colon carcinoma (continued). "Moreover, Il4/IL4R signaling trough Stat6 has been shown to promote the survival and proliferation of breast and colon cancer in a nude mice model, mainly via the upregulation of anti-apoptotic proteins PED, cFLIP, Bcl−xL and Bcl−2." (PMID 28927416, 2017). "To examine the relationship between exogenous IL-4 or IL-13 exposure and the expression of NOX1, we first determined whether the NOX1-expressing colon cancer cell lines under study possessed IL-4Rα, as has been reported previously." (PMID 28498822, 2017). "To examine the clinical relevance of our finding that in colon cancer cell lines IL-4 upregulates the expression of a functional NOX1-L isoform, we measured NOX1 expression in twenty tissue pairs consisting of surgically-resected colon cancers and their adjacent normal colonic mucosae." (PMID 28498822, 2017). "The sensitivity of CD133− non-CSC colon cancer cells to 5-fluorouracil and oxaliplatin was shown to strongly increase when interleukin-4 (IL-4), a cytokine present in colon cancer and absent in normal colon, was blocked by an IL-4 specific antibody." (PMID 24728412, 2014). "In addition, our results on lovo cells (colon cancer cells) shown that, TSLP is able to increase the expression of same cytokines inflammatory as Il-1, Il-4, Il-12 and IL-23 and in turn, these cytokines increase TSLP expression more than 4 times (results not shown)." (PMID 34573368, 2021). "When examined in resected tissues from patients with colon cancer, the authors found increased active NADPH oxidase 1 in the tumor tissue relative to the adjacent normal colon tissue, leading them to suggest that IL-4/IL-13-driven NADPH oxidase 1 expression may drive colon carcinogenesis." (PMID 29922293, 2018). "Additionally, in colon cancer stem cells, Survivin was regulated by IL4 through STAT-6 signaling and allowscancer cells to escape chemo sensitizing, which can be explained through our study that ERS inhibition may have reduced Survivin expression via IL4." (PMID 30326660, 2018). "However, when HT-29 cells were treated with IL-4 (50 ng/ml) for 5 min (rather than 96 h), we could not demonstrate an increase in DCF fluorescence compared to colon cancer cells exposed to medium alone." (PMID 28498822, 2017).
schistosomiasis (72 papers, 2008 to 2025). An infectious disease caused by parasitic trematodes of the genus Schistosoma that colonize human blood vessels and release eggs that can cause granulomatous reactions leading to acute (swimmer's itch or acute schistosomiasis syndrome) or chronic disease. "The chromosome 5q31–q33 Th2 cluster gene, which regulates the synthesis of interleukin 13, interleukin 4, and interleukin 5, is primarily linked to an increased risk of developing schistosomiasis." (PMID 41179539, 2025). "Since Th2 cytokines such as IL-4, IL-5, and IL-13 are implicated during schistosomiasis, it is worthy to evaluate such interleukins during the coinfection with human African trypanosomiasis." (PMID 37954132, 2023). "Type 2 cytokines (i.e., IL-4 and IL-13) are typically associated with the granulomatous response to parasite eggs in schistosomiasis." (PMID 35954255, 2022). "Specifically, TH2-associated cytokines IL-4, IL-5, IL-10, and IL-13 from splenic cell preparations appeared elevated in offspring exposed to treated maternal schistosomiasis." (PMID 35833137, 2022). "IL-4/IL-13 signalling in pulmonary tissue from individuals who died of schistosomiasis associated- pulmonary hypertension, underscoring the potential clinical relevance." (PMID 31024947, 2019). "Research by Adedokun and his colleagues suggests that the IL-4 promoter region is a predisposing factor for schistosomiasis and is critical in regulating the disease burden and that carriers of the rs2243250 T/T mutation are more severely affected." (PMID 31886304, 2019). "A major breakthrough was the identification of type 2 immune response, characterized by the T helper 2 cell associated cytokines such as interleukin 4 (IL-4) and IL-13, as a central regulator of disease progression in schistosomiasis." (PMID 29554131, 2018). "Type 2 immune response, featured by the T helper 2 cell associated cytokines such as IL-4 and IL-13, is the central regulator of disease progression in schistosomiasis, but the signals that induce it after infection remain elusive." (PMID 29554131, 2018). "Arginase 1 and Relmα, expression of both of which by macrophages is induced by IL-4/IL-13, are implicated in protective effects of M2 cells in schistosomiasis." (PMID 25144366, 2014). "The development of fibrosis in schistosomiasis is dependent on Th2 cytokines, and mice deficient in IL-4/IL-13 fail to upregulate Arg1." (PMID 19360123, 2009). "Previous studies with IL-4Rα−/− and some IL-4-deficient mice demonstrated that development of the Th2 response is critical for survival in schistosomiasis, especially during the early stages of infection." (PMID 18369473, 2008). "By identifying IL-4 and lymphocytes as robust biomarkers, this study paves the way for better surveillance strategies in high-risk regions, emphasizing the need for age-specific approaches in managing schistosomiasis." (PMID 40526709, 2025). "Signaling by IL-13 and IL-4 has been associate with the severity of schistosomiasis and fibrosis." (PMID 32922381, 2020). "Consequently, depending on the duration and magnitude of the infection, Th2 cytokines exhibit both protective (IL-4, acute infections) and pathogenic (IL-13, chronic infections) activity in the mouse model of schistosomiasis." (PMID 19360123, 2009). "Relevant studies revealed that the lung stage larvae of S. mansoni induced IL-4 production in rat (a semi-permissive host), whereas failed to induce the production of this cytokine in mice (a permissive host), suggesting that rat resistance to schistosomiasis is associated with Th2 cytokines." (PMID 36339337, 2022). "IL-4 is central in orchestrating the TH2-mediated immune response, promoting eosinophil activation and IgE production, both of which are hallmarks of schistosomiasis-associated granuloma formation." (PMID 40526709, 2025).